NGFR (nerve growth factor receptor)
Diseases named in the same sentence as NGFR in open-access papers (continued):
Sharing a sentence is not in itself a finding about the gene and the disease.
melanoma (continued). "NGFR is crucial to maintain basic properties of melanoma cells such as survival, migration and stemness and is associated with drug resistance, metastasis and cellular plasticity." (PMID 36435874, 2022). "In summary, we propose that the expression of Ecad and NGFR sub- classifies MBM and suggest that the Ecad-to-NGFR phenotype switch is a rate-limiting process which potentially indicates drug-response and intracranial progression states in melanoma patients." (PMID 36435874, 2022). "Ethanol can also upregulate the expression of nerve growth factor receptor (NGFR/CD271) through NF-κB signaling in human melanoma cells." (PMID 36291794, 2022). "Likely, phenotype switching is strongly affected by environmental cues such as inflammatory processes that foster dedifferentiation and enrichment of NGFR+ melanoma cells." (PMID 36435874, 2022). "Previous studies already proposed that NGFR+ melanoma feature a stem-like phenotype exhibiting cellular plasticity and drug-resistance." (PMID 36435874, 2022). "Several studies have shown that NGFR is involved in melanoma cell migration and invasion, establishing it as a mediator of phenotype switching by suppressing melanoma proliferation and simultaneously promoting invasion." (PMID 35693944, 2022). "The NGFR is a crucial regulator of phenotype switching in melanoma, is important in controling melanoma cell growth vs. invasiveness, and positively controls gene networks associated with melanoma progression." (PMID 36613518, 2022). "Next, we investigated the representation of Ecad and NGFR gene signatures in pre- and post-BRAFi/MEKi treated melanoma and observed a significant upregulation of NGFR-core genes such as EHD3 (p = 0.042)." (PMID 36435874, 2022). "We examined the levels of Ecad and NGFR in a lymph node metastasis (LN-MET) and concordant MBM (M1, M4) and validated a co-occurrence of melanoma cells that featured distinct (~35% NGFR+; ~50% Ecad+) and overlapping (~10% NGFR+/Ecad+) phenotypes." (PMID 36435874, 2022). "Another larger phase 2 trial combines CXCR2 and nerve growth factor receptor (NGFR) in CAR T cells to treat melanoma (NCT01740557)." (PMID 36366354, 2022). "A clinical trial (NCT01740557) was initiated to evaluate the efficacy of T cells transduced with CXCR2 and with nerve growth factor receptor (NGFR), associated with Recombinant Human IL-2 (Aldesleukin) infusion in melanoma." (PMID 35211124, 2022). "Considering the high plasticity of melanoma cells and our previous data, Ecad and NGFR are likely interconnected." (PMID 36435874, 2022). "BRAF-mutant melanoma cells with increased expression of EGFR are less sensitive to BRAF inhibitors and elevated expression of EGFR together with NGFR characterizes pre-resistant melanoma cells, which are selected during therapy and lead to treatment failure." (PMID 35565444, 2022). "High expression of NGFR in melanoma, thyroid, and lung cancers promoted cell proliferation and metastasis while reduced expression in liver, prostate, gastric, and bladder cancers induced apoptosis." (PMID 34299042, 2021). "As a result, NGFR should be used in combination with S100, especially in the setting of desmoplastic melanoma." (PMID 34449584, 2021). "NGFR, a marker of Schwannian differentiation, has been shown to be a useful confirmatory stain for desmoplastic melanoma even when staining with S100 protein was focal or weak in many cases." (PMID 34449584, 2021). "NGFR can function as an oncogene, enhancing cell proliferation and promoting cancer metastasis in thyroid carcinoma and melanoma, or as a tumor suppressor, stimulating cancer cell death in prostate, bladder, stomach, and liver cancers." (PMID 33996571, 2021). "As NGFR was proven to be useful for the diagnosis of desmoplastic melanoma, SOX10 was discovered to be as valuable." (PMID 34449584, 2021). "Even within tumors that were heterogeneous for NGFR, we observed an anticorrelation between T cell infiltrates and melanoma NGFR expression." (PMID 32770055, 2020).
melanoma (continued). "Lastly, pharmacologic NGFR inhibition restores tumor sensitivity to T cell attack in vitro and in melanoma xenografts." (PMID 32770055, 2020). "Consistently, our data rule out the involvement of EGFR in mediating ST3GAL1-dependent cell migration and invasiveness and narrow that of NGFR in ST3GAL1-dependent melanoma cell migration." (PMID 33203881, 2020). "First, it has been shown that in the vast majority of patient melanomas, NGFR-expressing cells lack expression of melanoma antigens, including MART-122,23." (PMID 32770055, 2020). "The nerve growth factor receptor CD271 (p75NTR, NGFR) was identified in 1968, functionally described in 1986, and associated with melanoma aggressiveness and metastasis in the late 1980s and early 1990s." (PMID 32878000, 2020). "This switching led to the upregulation of multiple melanoma stem cell markers including nerve growth factor receptor (NGFR) 46, ATP-binding cassette sub-family B member 5 (ABCB5) 47 and aldehyde dehydrogenase (ALDH) activity." (PMID 32483452, 2020). "We observed a significant anticorrelation between NGFR expression in melanoma cells and the presence of tumor-infiltrating T cells, characterized by CD3 expression and CD8 expression." (PMID 32770055, 2020). "Knockdown of NGFR markedly reduced the size and number of spheroid formation of melanoma cells, which can be rescued by ectopically expressed NGFR." (PMID 32686661, 2020). "Corroborating this set of results with clinical data, we show that an NGFR gene expression signature predicts resistance to immunotherapy in melanoma patients, again in line with the idea that NGFRhi tumor cells represent a pool of ICB-refractory cells." (PMID 32770055, 2020). "Here, the authors uncover a pre-existing NGFR-expressing, targetable subpopulation that is resistant to immunotherapy and other treatments in melanoma cells and preclinical models." (PMID 32770055, 2020). "In melanoma patients, a tumor-intrinsic NGFR signature predicts anti-PD-1 therapy resistance, and NGFRhi tumor fractions are associated with immune exclusion." (PMID 32770055, 2020). "Based on our finding above that an NGFR genetic signature predicts resistance to T cell killing, we also investigated the composition of melanomas in relation to their NGFR expression in situ." (PMID 32770055, 2020). "Enhanced expression of NGFR was shown in melanoma cells with acquired resistance to BRAF inhibition or combined BRAF/MEK inhibition, but it was also a part of a response to treatment preceding development of resistance to MEK inhibition." (PMID 31936151, 2020). "The nerve growth factor receptor CD271 is likewise expressed in melanocytes, melanoma cells and NCSCs and programs the maintenance of a stem-like and migratory phenotype via a comprehensive network of associated genes." (PMID 32878000, 2020). "CD271 (NGFR/p75NTR) acts as a molecular switch with divergent roles in melanocyte development and melanoma." (PMID 32899370, 2020). "Analysis of our cohort of 95 melanoma PDX, several of which were derived from BRAF inhibitor-relapsed tumors, showed that NGFR expression levels were significantly higher in the BRAF inhibitor-resistant melanomas." (PMID 32770055, 2020). "The highest increase was observed in melanoma cell populations resistant to trametinib, with more than 50% of NGFR-positive cells found in the 21_TRAR cell population." (PMID 31936151, 2020). "Coherently, one of the main markers of this state, namely the nerve growth factor receptor (NGFR) has been described as a putative melanoma CSC marker." (PMID 33202944, 2020). "The expression of AXL, EGFR and NGFR in melanoma has also been reported as markers for epithelial-mesenchymal transition and dedifferentiation indicating a loss of the original phenotype." (PMID 30850015, 2019).
melanoma (continued). "The relationship between senescence signalling and BRAF inhibitor resistance is best exemplified in melanoma where drug resistance is also typically accompanied by dedifferentiation markers such as NGFR, which is inducible by type II interferons (IFNγ)." (PMID 30850015, 2019). "Expression of five well-defined IFNγ targets, the PD-1 ligands PD-L1 and PD-L2, NGFR, antigen-presenting HLA-A, -B, and -C (HLA-ABC), and HLA-DR molecules was examined in a panel of 39 human melanoma cell lines with defined oncogenic driver mutations." (PMID 29977240, 2018). "Analysis of the IFNγ target proteins, HLA-ABC, HLA-DR, NGFR, PD-L1, and PD-L2, in a panel of 39 melanoma cell lines revealed that IFNγ stimulated cell surface expression of all five markers in only 13 melanoma cell lines tested." (PMID 29977240, 2018). "We noted that IFNγ stimulated the expression of HLA-ABC, HLA-DR, NGFR, PD-L1, and/or PD-L2 in the majority of melanoma cell lines." (PMID 29977240, 2018). "Melanoma cells express neuroectodermal marker transmembrane receptors such as nerve growth factor receptor (NGFR, CD271, neurotrophin receptor, Gene ID: 4804), which has been found to be a marker for melanoma-initiating cells." (PMID 28265786, 2017). "Drug-decreased percentage of Ki67high cells indicates reduced proliferation rate, whereas increased percentages of nerve growth factor receptor (CD271)high cells suggest selection of melanoma stem-like cells by vemurafenib and trametinib." (PMID 28829835, 2017). "Neural crest nerve growth factor receptor CD271 with an estimated frequency of 6.4%–75%; CD271+ melanoma cells are tumorigenic in immunodeficient (NOD/SCID) mice." (PMID 26978405, 2016). "The nerve growth factor receptor, CD271, is a protein expressed in the vast majority of human melanomas and in particular in melanoma stem cells." (PMID 26622576, 2015). "This abrogated recognition and killing by the cytotoxic pmel-1 T cells and favoured the outgrowth of melanomas with a dedifferentiated NGFR+ phenotype." (PMID 26530832, 2015). "CD271, known as the neural crest nerve growth factor receptor, is the marker of bone marrow mesenchymal stem cells (MSCs) and human melanoma-initiating cells." (PMID 24893164, 2014). "Notably, melanoma dedifferentiation marker NGFR and drug resistance marker AXL were upregulated in the tumor cell cycle G2/M program, suggesting potential interactions with mregDC that remain to be elucidated." (PMID 40890106, 2025). "Additionally, melanoma cells can transition to a neural crest-like state, characterized by the expression of NGFR (nerve growth factor receptor) and other markers, which represent melanocyte precursors." (PMID 40872623, 2025). "The low-affinity nerve growth factor receptor p75NTR is a putative marker of normal oral and esophageal keratinocyte stem cells and has also been suggested as a marker of CSCs in malignant melanoma and esophageal carcinoma, as well as a determinant of poor prognosis in OSCC." (PMID 41228340, 2025). "Furthermore, MITF−/low melanoma cells strongly expressed the Nerve Growth Factor Receptor (NGFR/CD271) identified as a marker of MICs and, partially, the epithelial-to-mesenchymal transition (EMT) marker ZEB1." (PMID 38191367, 2024). "Interestingly, the ZEB1high clone from MM10 displayed NGFR positivity, and NGFR levels were significantly higher in ZEB1high melanoma cells." (PMID 38519642, 2024). "Interestingly, while some ZEB1 peaks were conserved in MDA-MB-231, peaks in ZEB2, SOX10 and NGFR were only found in melanoma cells." (PMID 38519642, 2024). "In the case of melanoma, EVs enriched with nerve growth factor receptor (NGFR) were found to facilitate lymphangiogenesis and metastasis through the activation of ERK and NF-κB pathways in LECs, resulting in proliferation and upregulation of adhesion molecules." (PMID 39682225, 2024).
melanoma (continued). "The degradation of sortilin could be responsible for decreased cell migration and invasion, as sortilin is required for the interaction of proNGF, a neurotrophin produced by melanoma, with NGFR in promoting melanoma migration." (PMID 39229155, 2024). "Remarkably, the NCSC-like cellular state in BRAF-mutated melanoma has also been associated with the development of non-genetic resistance to MAPK-targeted therapies in a NGFR/FAK/AKT-dependent manner." (PMID 36774337, 2023). "In conclusion, our findings suggest NGFR as promising therapeutic target in melanoma." (PMID 36638181, 2023). "Moreover, RNA-seq data had suggested that this was due to NGFR-mediated down-regulation of NK cell activating ligands in melanoma cells." (PMID 36638181, 2023). "In addition to transcription factors, a prominent role in melanoma phenotype switching is played by the CD271/NGFR neurotrophin receptor which promotes a stem-like and migratory phenotype." (PMID 36765773, 2023). "Humanized cytotoxic antibodies against NGFR are in preclinical trials and might advance specific targeting of this aggressive melanoma cell subtype." (PMID 36638181, 2023). "Hence, NGFR orchestrates immune control antagonizing pathways to protect melanoma cells from NK cell clearance, which ultimately favors metastatic disease." (PMID 36638181, 2023). "Particularly, NGFR expression seems involved in melanoma cell spreading to the brain." (PMID 36941697, 2023). "In addition, NGFR has also been shown to be functionally involved in providing resistance to melanoma-specific T cell attack in vitro." (PMID 36638181, 2023). "In contrast, impaired NK cell killing of NGFR-overexpressing cells could almost completely be rescued by treating NGFRhigh melanoma cells with MF438, an inhibitor of the fatty acid desaturase SCD." (PMID 36638181, 2023). "Melanoma cells release significant levels of neurotrophins and express the Trk receptors and NGFR." (PMID 36941697, 2023). "To address whether NGFR-induced suppression of NK cell activation results in tumor cell resistance toward NK cell attack, we cocultured human NK cells together with melanoma cells and measured their lysis by a flow cytometry–based approach." (PMID 36638181, 2023). "To address this hypothesis, we overexpressed NGFR in human melanoma xenografts and analyzed tumor-infiltrating innate immune cells." (PMID 36638181, 2023). "Last, as NK cells are important guardians of circulating tumor cells, we asked whether NGFR-mediated NK cell evasion drives melanoma metastasis formation." (PMID 36638181, 2023). "Analysis of matched tumor dissociates confirmed that de-differentiated PD1 PROGs were derived from tumors with less proliferative (trend toward lower % Ki67+ melanoma) and more de-differentiating (increased melanoma expressing the stem cell marker NGFR) melanoma cells." (PMID 36934113, 2023). "Indeed, NGFR expression by melanoma cells, as assessed by immunohistochemistry, was inversely correlated with the presence of CD8+ T cells." (PMID 35432344, 2022). "The epigenetic regulator EZH2, was recently shown to coordinate melanoma cell dedifferentiation (associated with a gain in ZEB1 and NGFR) with downregulation of MHC class I (HLA-A/B/C) and antigen presentation machinery (i.e. antigen processing genes TAP1/2 and immunoproteasome subunits PSMB8/9)." (PMID 35432344, 2022). "Concordantly, NGFR was highly expressed in chemoresistant melanoma cells." (PMID 35163127, 2022).
melanoma (continued). "Melanoma cells expressing NGFR exhibit increased migratory, invasive and survival capacities and the knockdown of this TNF-receptor family member revealed a network of NGFR/CD271-associated genes that facilitate and maintain different phenotypes." (PMID 35163127, 2022). "In line with this, we observed a higher expression of MRD-associated genes in NGFRhigh than NGFRlow tumors, indicating that NGFR+ melanoma cells are indeed responsible for intracranial relapse and progression and might emerge under hypoxic conditions." (PMID 36435874, 2022). "NGFR signaling also plays a critical role in acquired melanoma resistance to BRAF/MEK inhibitors." (PMID 36291794, 2022). "In addition, we observed a significant correlation between the promoter of invasiveness LOXL3 and expression of NGFR in primary (PT) and metastatic (EM) melanoma." (PMID 36435874, 2022). "High levels of NGFR were also associated with other metabolic stress inducers, further indicating that YY1 knockdown mimics a metabolic stress program associated with an increased invasion potential in melanoma." (PMID 35693944, 2022). "In line with this, and alike others, we observed that melanoma cells can undergo further dedifferentiation, losing neural crest features that are prominent in the intermediate state, such as expression of nerve growth factor receptor (NGFR), Erb-B2 receptor tyrosine kinase 3 (ERBB3), and SOX10." (PMID 36434616, 2022). "Moreover, the authors demonstrated that conditioned medium from engineered T cells is sufficient to decrease the expression of MDA and stimulate NGFR expression in human melanoma cells." (PMID 35432344, 2022). "In addition, NGFR, a key effector in melanoma invasion and phenotype switching, was among the most upregulated genes after YY1 knockdown." (PMID 35693944, 2022). "Notably, ZEB1 increases the expression of NCSC markers, such as NGFR, a major regulator of phenotype switching in melanoma." (PMID 35432344, 2022). "Thus, the targeting of NGFR induces apoptosis of BRAFi/MEKi-resistant melanoma cells and prevents melanoma invasion and metastasis formation in vivo." (PMID 36613518, 2022). "GSEA and expression analysis revealed that NGFR+ tumors indeed expressed high levels of MRD-associated genes, particularly the MRD-associated gene EHD3 was upregulated in post-treatment melanoma and was significantly more highly expressed in NGFRhigh MBM." (PMID 36435874, 2022). "In addition to its established role in melanoma initiation and metastasis, NGFR has been shown to regulate genes involved in mitotic stability and DNA repair." (PMID 33800547, 2021). "prominin-1) and CD271 (nerve growth factor receptor), which have recently been identified as critical molecules that promote melanoma initiation and metastasis, remains unclear." (PMID 35003391, 2021). "Intriguingly, while some NCSC factors, such as SOX10 and YY1, are activated upon melanoma formation and are required for melanoma growth, other NCSC-associated factors, such as CD271/NGFR/p75NTR, PAX3, and FOXD3 promote melanoma cell invasiveness and metastasis formation." (PMID 34417458, 2021). "Although inhibiting a single target gene, such as ROCK1 and NGFR, can sensitize vemurafenib-resistant melanoma cells, our results showed that pair-wise perturbation of ROCK1 + NF2 or NGFR + NF2 conferred a strong protective phenotype during vemurafenib treatment." (PMID 34106558, 2021). "Importantly, knockdown of NGFR increased the frequency of DNA damage in melanoma cells and enhanced their sensitivity to fotemustine." (PMID 33800547, 2021). "Furthermore, gene set enrichment analysis (GSEA) revealed that NGFR-positive melanoma cells were particularly enriched for genes participating in NER and DNA replication." (PMID 33800547, 2021). "Notably, NGFRhigh expressing melanoma cells also showed increased PD-L1 expression, with NGFR and PD-L1 protein synthesis both being under translational control via the eIF4F complex." (PMID 34604096, 2021).